RNU6-370P (RNA, U6 small nuclear 370, pseudogene)
Gene: Small nuclear RNA gene on chromosome 2 (24,045,835 to 24,045,938, forward strand). Ensembl gene ENSG00000222940.
Homologues: Orthologues: chimpanzee U6 (99% identical), macaque U6 (97% identical), rabbit U6 (86% identical), dog U6 (80% identical), mouse Gm25716 (75% identical). Paralogues in human: RNU6-183P (88% identical), RNU6-1311P (87% identical), RNU6-454P (87% identical), RNU6-961P (87% identical), RNU6-1094P (86% identical), RNU6-204P (86% identical), RNU6-655P (86% identical), RNU6-944P (86% identical), RNU6-1040P (85% identical), RNU6-115P (85% identical), RNU6-11P (85% identical), RNU6-1243P (85% identical), and 1284 more.